SEPTIN14 (septin 14)
Description:
Filament-forming cytoskeletal GTPase (Probable). Involved in the migration of cortical neurons and the formation of neuron leading processes during embryonic development (By similarity). Plays a role in sperm head formation during spermiogenesis, potentially via facilitating localization of ACTN4 to cell filaments.
Synonyms: SEPT14; FLJ44060; Septin-14
Tractability: PROTAC: ubiquitination databases record sites on it.
Gene: Protein-coding gene on chromosome 7 (55,793,540 to 55,862,755, reverse strand). Ensembl gene ENSG00000154997.
Subcellular location: Cytoplasm; Cytoplasm, cytoskeleton; Cell projection, axon; Cell projection, dendrite; Perikaryon; Cytoplasm, perinuclear region; Cytoplasmic vesicle, secretory vesicle, acrosome
Gene Ontology:
Molecular function: protein binding; GTPase activity; molecular adaptor activity; GTP binding
Biological process: protein localization to perinuclear region of cytoplasm; spermatid development; cytoskeleton-dependent cytokinesis; intracellular protein localization; neuron migration
Cellular component: acrosomal vesicle; cytoplasm; cytoskeleton; axon; cell division site; dendrite; microtubule cytoskeleton; perikaryon; perinuclear region of cytoplasm; septin complex; septin ring
Genetic constraint (gnomAD): Loss-of-function variants: 6 observed, 5.77 expected, observed/expected ratio (o/e) 1.04, 90% interval 0.56 to 1.8. That is too few expected variants to judge how well the gene tolerates losing a copy. Missense variants: 63 observed, 57.4 expected, observed/expected ratio (o/e) 1.1, 90% interval 0.89 to 1.35. Synonymous variants: 15 observed, 19.93 expected, observed/expected ratio (o/e) 0.75, 90% interval 0.5 to 1.16.
Homologues: Orthologues: chimpanzee SEPTIN14 (99% identical), macaque SEPTIN14 (90% identical), pig SEPTIN14 (83% identical), dog SEPTIN14 (82% identical), mouse Septin14 (76% identical), rat Septin14 (76% identical), guinea pig SEPTIN14 (67% identical), Drosophila melanogaster Septin2 (57% identical), Caenorhabditis elegans unc-61 (42% identical), Drosophila melanogaster Septin1 (34% identical), tropical clawed frog septin5 (33% identical), zebrafish zgc:63587 (24% identical), and 15 more. Paralogues in human: SEPTIN10 (72% identical), SEPTIN11 (62% identical), SEPTIN8 (62% identical), SEPTIN6 (60% identical), SEPTIN7 (41% identical), SEPTIN5 (33% identical), SEPTIN2 (33% identical), SEPTIN1 (31% identical), SEPTIN3 (30% identical), SEPTIN9 (30% identical), SEPTIN12 (26% identical), TMEM250 (5% identical).
Diseases named in the same sentence as SEPTIN14 in open-access papers:
SEPTIN14 is named in the same sentence as 25 diseases in open-access papers, as found by Europe PMC text mining. Sharing a sentence is not in itself a finding about the gene and the disease. The quoted sentences say what the papers report.
glioblastoma (10 papers, 2014 to 2025). The most malignant astrocytic tumor (WHO grade IV). "Two fusions identified as having oncogenic potential in our study had previously been associated with glioblastoma: FGFR3::TACC3 and EGFR::SEPTIN14." (PMID 36002559, 2022). "Two fusions had previously been associated with glioblastoma: FGFR3::TACC3 and EGFR::SEPTIN14." (PMID 36002559, 2022).
male infertility (5 papers, 2014 to 2022). The inability of the male to effect fertilization of an ovum after a specified period of unprotected intercourse. "It was shown that septin 14 expression levels are critical for human spermatogenesis and decreased expression is associated with the pathogenesis of male infertility." (PMID 24799881, 2014). "Septin14 is an important spermatogenesis related gene involved in the pathogenesis of male infertility that has not been well studied." (PMID 33791027, 2021).
tumor (2 papers, 2010 to 2020). "Studies have found that aberrant expression of septin, may induce antiproliferative and tumor suppressive effects, and somatic variants of SEPTIN14 have been demonstrated in skin and gastrointestinal cancers." (PMID 33680922, 2020).
SEPTIN14 also shares sentences with these, for which no sentence is quoted: cancer (7 papers); glioma (4); teratozoospermia (3); colorectal cancer (2); Parkinson disease (2); acute myeloid leukemia (1); Anxiety (1); Azoospermia (1); colon adenocarcinoma (1); Colon Cancer (1); depression (1); infertile (1); invasive breast carcinoma (1); low grade glioma (1); lung adenocarcinoma (1); pilocytic astrocytoma (1); prostate adenocarcinoma (1); prostate carcinoma (1); rectal adenocarcinoma (1); sarcoma (1); somatotropinoma (1); spermatogenic failure (1).